HOTAIR (HOX transcript antisense RNA)
Diseases named in the same sentence as HOTAIR in open-access papers (continued):
Sharing a sentence is not in itself a finding about the gene and the disease.
cervical carcinoma (continued). "After establishing HOTAIR’s role in modulating key signaling pathways in cervical cancer (CC), we conducted a meta-analysis that revealed elevated levels of PI3K, AKT, HIF1α, and β-catenin proteins in CC tumor samples compared to healthy controls, alongside reduced levels of GSK3β." (PMID 39273054, 2024). "Several lncRNAs, including HOTAIR, H19, mucosa-associated lymphoid tissue 1 (i.e., MALT1), growth arrest-specific 5 (i.e., GAS5), cervical carcinoma high expressed 1 (i.e., CCHE1), and Pvt1 oncogene (i.e., PVT1), are crucial in tumorigenesis, invasion, metastasis, and radio-resistance." (PMID 37081411, 2023). "In conclusion, MKL1 is an important promoter of HOTAIR in cervical cancer invasion and migration." (PMID 36890809, 2023). "Similarly, propofol repressed the cell viability, invasion, colony formation and migration in cervical cancer cells via targeting HOTAIR and modulating miR-129-5p/RPL14 axis." (PMID 36438563, 2022). "HOTAIR, GAS5, TUSC8, and lncRNA-LET may be valuable biomarkers for predicting cervical cancer prognosis, as they are associated with invasion and metastasis." (PMID 36144454, 2022). "Moreover, miR-22 targeted rs2366152C of lncRNA HOTAIR, resulting in downregulation of lncRNA HOTAIR in cervical cancer cells." (PMID 36438563, 2022). "The results showed that HOTAIR regulates the sensitivity of cervical cancer cells by acting on P21." (PMID 35692795, 2022). "For example, lncRNA HOTAIR downregulation enhances cervical cancer sensitivity to radiotherapy." (PMID 35067169, 2022). "Furthermore, HOTAIR expression level can act as an independent biomarker for OS in cervical cancer patients." (PMID 36438563, 2022). "Moreover, blockade of HOTAIR by artesunate or propofol shows promise for further development of this lncRNA as a potential therapeutic target in cervical cancer." (PMID 35456001, 2022). "Moreover, high expression of HOTAIR was associated with worse OS and DFS in cervical cancer patients." (PMID 36438563, 2022). "For example, HOTAIR is upregulated in cervical cancer cells but downregulated in oral cancer cells." (PMID 36230902, 2022). "In cervical cancer, the lncRNA HOTAIR is also connected with stemness acquisition." (PMID 36685972, 2022). "HOTAIR/miR-214-3p/Wnt/β-catenin signal pathway might played important regulated roles in HPV16 positive cervical cancer." (PMID 34320988, 2021). "In order to explore whether HOTAIR participates in regulating stem properties of cervical cancer, the levels of HOTAIR in two stem-like cells and their parental cells were evaluated." (PMID 34539782, 2021). "HOTAIR knockdown could increase radiosensitivity of PCa and cervical cancer by regulating autophagy and EMT." (PMID 34367966, 2021). "Recently, HOTAIR has been conformed as molecular sponge for several miRNAs in various malignant tumors including colorectal cancer, hepatocellular carcinoma, pancreatic carcinoma and cervical cancer." (PMID 34320988, 2021). "Actually, HOTAIR's pivotal role on stem cells of various types of malignant tumors has been reported previously, but the role of HOTAIR on the phenotype of cervical cancer stem cells was currently unknown." (PMID 34539782, 2021). "Contrasting reports exist on the effect of E7 on expression of the HOX transcript antisense intergenic RNA (HOTAIR): one study indicated that HOTAIR was highly expressed in cervical cancer tissue and cell lines, whilst others suggest HOTAIR is in fact downregulated." (PMID 33427604, 2021). "HOTAIR is overexpressed in ovarian cancer, and it is associated with stage, lymph node metastases and poor survival; similarly, HOTAIR is overexpressed in cervical cancer and in endometrial carcinoma in which it is also associated with cisplatin resistance acquisition." (PMID 34576322, 2021).
cervical carcinoma (continued). "The overexpression of HOTAIR resulted in statistically more invaded either HeLa or SiHa cells through the pores, while interference targeting HOTAIR revealed a significant decrease in invaded cervical cancer cells." (PMID 34539782, 2021). "And once HOTAIR was knocked down in HPV16 positive cervical cancer cells, miR-214-3p could escape from the absorption of HOTAIR and further lead to its target gene β-catenin been degraded." (PMID 34320988, 2021). "The current research showed that HOTAIR was highly expressed and could be used as an indicator of poor prognosis of cervical cancer." (PMID 34320988, 2021). "Combining with the previous results, HOTAIR and miR-214-3p could both directly regulated the expression of β-catenin, and HOTAIR could upregulated the expression of β-catenin by targeted adsorbing miR-214-3p in cervical cancer cells." (PMID 34320988, 2021). "Interestingly, HOTAIR also promoted the migration and invasion level of cervical cancer cells, just like cervical cancer stem-like cells." (PMID 34539782, 2021). "Furthermore, HOTAIR levels have shown to be strictly controlled by the HPV E7 protein in cervical cancer." (PMID 34320988, 2021). "HOTAIR could rely on this response element to serve as a sponge against miR-214-3p, and inhibited the function of miR-214-3p in cervical cancer cells." (PMID 34320988, 2021). "Moreover, the increased HOTAIR levels in the serum of cervical cancer patients is also indicative of the metastatic tumor phase, adenocarcinoma, lymphatic node metastasis and tumor recurrence." (PMID 32154165, 2020). "HOTAIR expression causes the up regulation of the vascular endothelial growth factor (VEGF), matrix metalloproteinase-9 (MMP-9) and EMT-related genes thus promoting tumor aggressiveness in cervical carcinoma." (PMID 32154165, 2020). "Moreover, the over expression of HOTAIR has demonstrated to regulate diverse metabolic functions such as the activation of mTOR pathway in cervical carcinoma cell lines Hela, CaSki, and C33A, as well as the activation of Notch-Wnt signaling in SiHa cells." (PMID 32154165, 2020). "Indeed, HOTAIR has shown to alter the miR-143-3p/BCL2 axis favoring cervical cancer cell growth and miR-23b/MAPK1 axis contributing to cell proliferation and metastasis." (PMID 32154165, 2020). "Through its interaction with HIF-1a, HOTAIR is also able to induce radio-resistance in cervical cancer cells, suggesting that HOTAIR-HIF-1α axis might be a crucial mechanism for radio-resistance modulation hypoxia-induced." (PMID 31072041, 2019). "Similarly, LncRNA MALAT1 and HOTAIR were reported to predict the poor clinical outcome of patients with cervical cancer." (PMID 29720427, 2018). "However, the lncRNA HOTAIR has been reported to target the Notch signaling pathway in cervical cancer cells." (PMID 30445766, 2018). "However, the mechanism of how HOTAIR interacted with HIF-1α in cervical cancer cells exposed to radiotherapy needs to be further investigated." (PMID 30355300, 2018). "Additionally, increased HOTAIR expression in cervical cancer cells is reported to enhance aggressive characteristics, such as invasion, proliferation, and radioresistance, via suppression of p21." (PMID 28872613, 2017). "Furthermore, we recently demonstrated, in a study of 215 cervical cancer and 430 cancer-free cases, that rs920778 is strongly correlated with the upregulation of HOTAIR." (PMID 28649178, 2017). "In our previous study, the increased expression of a large number of genes in cervical cancer cases, was explained through probable abrogation of lncRNA HOTAIR function in PRC2-LSD1 complex recruitment and repression of gene expression, under the influence of E7." (PMID 28402266, 2017). "Notably, HOTAIR was the most investigated lncRNA in cervical cancer, therefore, articles explored HOTAIR as a new biomarker in the diagnosis and treatment of cervical cancer is possibly the most promising." (PMID 28977961, 2017).
cervical carcinoma (continued). "The study of HOTAIR expression in the sera of cervical cancer patients indicate that the level of circulating HOTAIR may serve as a promising predicting and therapeutic target in cervical cancer." (PMID 27467165, 2016). "Given HOTAIR promoted metastasis of cervical cancer, we further speculated donwregulation of HOTAIR expression mediated an anti-metastatic effect of ART on cervical cancer." (PMID 27736969, 2016). "These lines of evidence suggest that the TT genotype of SNP rs920778 in the HOTAIR gene may play crucial roles in the development of cervical cancer by influencing HOTAIR expression." (PMID 27467165, 2016). "We previously found that HOTAIR is upregulated during cervical cancer." (PMID 27323817, 2016). "This study revealed that expression of serum HOTAIR increased in cervical cancer patients." (PMID 27323817, 2016). "Increased HOTAIR levels are present during advanced-stage cervical cancer." (PMID 27323817, 2016). "This speculation was supported by the observation that HOTAIR overexpression partially abolished the effect of ART on cervical cancer cell migration and invasion." (PMID 27736969, 2016). "A positive correlation of HOTAIR rs920778 polymorphism with the risk of human cancers has been analyzed extensively, but the association between HOTAIR expression and the different genotype of rs920778 polymorphism in cervical cancer was not investigated." (PMID 27467165, 2016). "We previously reported that EMT correlates with HOTAIR expression in cervical cancer patients." (PMID 27323817, 2016). "HOTAIR expression also reflected the malignant development of cervical cancer, to some extent." (PMID 27897239, 2016). "Taken together, these results suggested that HOTAIR may have a significant role in the pathogenesis of cervical cancer." (PMID 27323817, 2016). "Additionally, we discussed the relationships between high HOTAIR expression and the occurrence and development of cervical cancer." (PMID 27897239, 2016). "High expression of HOTAIR affected the occurrence and development of cervical cancer." (PMID 27897239, 2016). "Our results showed that ART significantly decreased HOTAIR expression in cervical cancer cells." (PMID 27736969, 2016). "In summary, we found that cervical cancer patients had elevated serum HOTAIR levels." (PMID 27323817, 2016). "Taken together, our data revealed that ART may elicit anti-metastatic effect against cervical cancer by inhibition of HOTAIR expression, which resulted in the decrease of COX-2 expression." (PMID 27736969, 2016). "We therefore hypothesized that HOTAIR regulating COX-2 expression might be involved in the effect of ART on cervical cancer." (PMID 27736969, 2016). "We found that ART inhibited cervical cancer metastasis and HOTAIR expression." (PMID 27736969, 2016). "Taken together, our findings suggest that HOTAIR may promote cervical cancer cell migration and invasion through the upregulation of VEGF and MMP-9 expression." (PMID 25405331, 2015). "Also, we examined the molecular events that occur downstream of HOTAIR involvement in cervical cancer migration and invasion." (PMID 25405331, 2015). "Together, our findings suggest that HOTAIR may represent a potential biomarker and therapeutic target for cervical cancer." (PMID 25405331, 2015). "Although HOTAIR has been shown to play a critical role in the progression of breast, liver, colon and pancreatic cancers, little is known about the molecular mechanisms in cervical cancer." (PMID 25405331, 2015). "Furthermore, HOTAIR knockdown inhibited proliferation, migration and invasion of human cervical cancer cell lines." (PMID 25405331, 2015). "Furthermore, HOTAIR knockdown inhibits autophagy and migration of cervical cancer cells." (PMID 36230902, 2022).
cervical carcinoma (continued). "HOTAIR expression is also lower in many cervical lesions and cancers, although a more detailed analysis revealed that there may be two distinct groups of cervical cancer cases, those that express high HOTAIR and those that express low HOTAIR." (PMID 36366537, 2022). "Interestingly, HOTAIR plays an oncogenic role in cervical cancer by promoting cell proliferation, migration, invasion, and autophagy, inhibiting cell apoptosis, stimulating angiogenesis, accelerating cell cycle progression, and inducing epithelial–mesenchymal transition." (PMID 35456001, 2022). "These researches indicated that HOTAIR might play an important roles in cervical cancer." (PMID 34320988, 2021). "However, the role of HOTAIR and miR-203 in acquisition of cervical cancer stem cells is still unknown." (PMID 34539782, 2021). "Finally, Wnt/β-catenin dependent pathway might activate by HOTAIR/ miR-214-3p axis in cervical cancer cells." (PMID 34320988, 2021). "Radiotherapy might inhibit cervical cancer cell growth through HOTAIR/HIF-1α pathway." (PMID 30355300, 2018). "Therefore, we speculated that in cervical cancer cells, hypoxia upregulated HOTAIR expression to sponge miR-217, thus to promote HIF-1α expression." (PMID 30355300, 2018). "Furthermore, it implicates that HOTAIR-HIF-1α axis might be a potential target for cervical cancer radiotherapy." (PMID 30355300, 2018). "Using immortalized cervical cancer cells and an animal model, we demonstrated that HOTAIR reduces radiation-induced apoptosis and leads to cellular radioresistance via targeting p21; in contrast, the knockdown of HOTAIR promoted cellular apoptosis and re-sensitized cancer cells to radiotherapy." (PMID 28649178, 2017). "HOTAIR may be a useful target for treatment of cervical cancer patients." (PMID 27323817, 2016). "Thus, HOTAIR may contribute to malignant cervical cancer cell phenotypes via the activation of Wnt-Notch signalling and EMT." (PMID 27323817, 2016). "Therefore, HOTAIR exerts pro-oncogenic activities in cervical cancer and may promote a more aggressive and metastatic phenotype." (PMID 25405331, 2015). "Therefore, downregulation of HOTAIR decreased the migration of cervical cancer cells." (PMID 25405331, 2015). "Moreover, HOTAIR may promote cervical cancer progression by inducing cell migration and invasion through the upregulation of VEGF, MMP-9 and expression of EMT-related genes." (PMID 25405331, 2015). "Thus, HOTAIR may represent a potential therapeutic target and a prognostic marker for cervical cancer." (PMID 25405331, 2015). "Specifically, oncogenic lncRNAs, such as HOTAIR and MALAT1, are significantly upregulated in EVs from cervical cancer patients, while the tumor-suppressive lncRNA MEG3 is significantly downregulated." (PMID 40809518, 2025). "They found increased expression of four LncRNAs—HOTAIR, PVT1, XLOC‐000303, and AL592284.1—in cervical cancer compared to healthy samples, suggesting their potential as biomarkers for cancer prediction." (PMID 40953835, 2025). "Our literature review and background research identified LncRNA HOTAIR as a crucial modulator of the Wnt/β-catenin and PI3K/AKT pathways in cervical cancer (CC), even in the presence of Wnt inhibitors." (PMID 39273054, 2024). "For example, in cervical cancer, several lncRNAs, including RP11-480112.5, ASB16-AS1, HOTAIR, CASC11, CALML3-AS1, and DANCER, are involved in modulating Wnt Signaling pathways." (PMID 35406713, 2022). "Artesunate inhibited the expression of HOTAIR and downregulated the COX-2 expression, leading to anti-metastatic ability of artesunate in cervical cancer." (PMID 36438563, 2022). "HOTAIR interacted with COX-2 and increased COX-2 expression and catalytic activity, resulting in promotion of invasion and migration in cervical cancer." (PMID 36438563, 2022). "Therefore, HOTAIR may be a potential target against cervical cancer." (PMID 36685972, 2022).
cervical carcinoma (continued). "HOTAIR promoted cell motility and metastasis via modulation of MMP-9, VEGF and EMT-related genes in cervical cancer." (PMID 36438563, 2022). "For example, HOTAIR interacted with miR-29b, miR-203, and miR-214-3p, and targeted PI3K and Wnt pathways in cervical cancer." (PMID 35406713, 2022). "Our results confirmed that HOTAIR expression have positive correlation with HPV16 E7, suggested that there was indeed interaction between lncRNA HOTAIR and HPV16 E7 in cervical cancer cells." (PMID 34320988, 2021). "Our results showed that expression of HOTAIR was up-regulated, while that of miR-214-3p was down-regulated in HPV16-positive cervical cancer cells." (PMID 34320988, 2021). "In another word, HOTAIR and β-catenin acted as a pair of competitive endogenous RNA in HPV16 positive cervical cancer through competing binding to miR-214-3p." (PMID 34320988, 2021). "Notably, HPV16 E7 maybe play a key regulatory role in this process, because HOTAIR inhibition roles against miR-214-3p no longer existed due to the loss or decline of E7 expression in cervical cancer cells." (PMID 34320988, 2021). "In conclusion, we found a novel regulatory axis: HOTAIR/miR-214-3p/β-catenin, exerts a ceRNA effect, involved in proliferation and apoptosis of HPV16 positive cervical cancer cells." (PMID 34320988, 2021). "However, the role of HOTAIR in cervical cancer stem cells is still unknown." (PMID 34539782, 2021). "The potential signal pathway regulated by HOTAIR/miR-214-3p was predicted by KEGG enrichment analysis and confirmed by qPCR and WB analysis in cervical cancer cells." (PMID 34320988, 2021). "Our previous data showed that HOTAIR participated in chemoresistance of cervical cancer through triggering epithelial-to-mesenchymal transition (EMT), which was considered the main factor responding for stemness acquisition by HOTAIR." (PMID 34539782, 2021). "Also several lncRNAs, comprising among others HOTAIR, MALAT1, GAS5, and MEG3, have shown to be associated with various pathogenic processes such as tumor progression, invasion as well as therapeutic resistance and emerged as new diagnostic and prognostic biomarkers in cervical cancer." (PMID 32154165, 2020). "Exosomal lncRNA MALAT1, HOTAIR, and MEG3 are differentially expressed in cervical cancer cervicovaginal lavage samples, which suggests that these lncRNAs can be promising biomarkers in detecting cervical cancer." (PMID 31360701, 2019). "Tissue microarray and immunohistochemical staining were used to assess the correlation between HOTAIR and MKL1 in Cervical cancer tissues in vivo." (PMID 29391067, 2018). "We further informed that the expression of HOTAIR and MKL1 were positively correlation in cervical cancer patient." (PMID 29391067, 2018). "B. HOTAIR and HIF-1α expression was upregulated in cervical cancer cells than normal cervical epithelial cells (NCECs)." (PMID 30355300, 2018). "In this study, we investigated the expression of HOTAIR in cervical cancer cells exposed to radiotherapy and analyzed the impact of HOTAIR and HIF-1α on the radiotherapy effect in cervical cancer cells." (PMID 30355300, 2018). "Then we carried out a meta-analysis on the relationship between the expressions of HOTAIR/PVT1 and the OS of patients with cervical cancer." (PMID 28977961, 2017). "Down-regulation of HOTAIR, with corresponding upregulation of the HOTAIR target HOXD10, has been observed in cervical cancer." (PMID 28862667, 2017). "The present data additionally demonstrated that HOTAIR positively regulated COX-2 expression and catalytic activity in cervical cancer cells." (PMID 27736969, 2016). "LcnRNAs of HOTAIR, CCAT2, MALAT1, EBIC and MEG3 have been reported to be involvled in cervical cancer metastasis." (PMID 27736969, 2016).